NUSAP1 (nucleolar and spindle associated protein 1)
Diseases named in the same sentence as NUSAP1 in open-access papers (continued):
Sharing a sentence is not in itself a finding about the gene and the disease.
tumor (continued). "Furthermore, NUSAP1 expression exhibited a significant positive correlation with tumor mutation burden (TMB), with LUAD samples featuring high NUSAP1 expression showing markedly elevated TMB values compared to those with low NUSAP1 expression." (PMID 39781524, 2025). "Inhibition of NUSAP1 expression enhanced tumor cell sensitivity to 5-FU." (PMID 40393971, 2025). "This gap represents a promising direction for future research, as elucidating this relationship could facilitate a deeper understanding of NUSAP1’s unique role in tumor development and its potential applications in clinical diagnosis and treatment." (PMID 40535133, 2025). "To investigate whether NUSAP1 influences tumor growth in vivo, we first conducted a soft agar assay in vitro." (PMID 40393971, 2025). "Furthermore, as previously discussed, NUSAP1 promotes chemotherapy resistance by enhancing DNA damage repair and compromises immunotherapy efficacy by facilitating tumor immune escape." (PMID 40535133, 2025). "Simultaneously, the high expression of NUSAP1 may suppress immune responses, indicating its potential as a novel immune checkpoint and offering a new avenue for optimizing tumor immunotherapy." (PMID 40535133, 2025). "Future research exploring the interactions between NUSAP1 and other tumor-related genes may help develop more effective therapeutic strategies, advancing the progress of personalized medicine." (PMID 39975552, 2025). "This process is accompanied by the decreased expression of multiple proteins, such as NUSAP1, indicating that the downregulation of NUSAP1 may suppress GC cell proliferation and enhance the anti-tumor efficacy of medicines." (PMID 40535133, 2025). "Our findings suggested that NUSAP1 may promote cancer cell proliferation, influence cell cycle related pathways, and inhibit cell apoptosis, thereby contributing the survival of tumor cells." (PMID 38441732, 2024). "According to the IHC score, NUSAP1 was overexpressed in the tumor tissues (t = 4.473, P < 0.001)." (PMID 38229038, 2024). "By analyzing the TCGA-LUAD cohort utilizing the CAMOIP online tool, we found that high-NUSAP1 expression group exhibited higher scores for tumor mutation burden (TMB) and neoantigen loads (NALs), but not MANTIS." (PMID 39430250, 2024). "Furthermore, VEGFA 26, known to hinder tumor immunotherapy, demonstrated a positive correlation with the expression levels of NUSAP1 in GBM, KICH, KIRC, KIRP, LUAD, PAAD, SARC, and SKCM." (PMID 37781040, 2023). "Moreover, utilizing the UALCAN database, we further conducted an analysis of NUSAP1 protein levels between normal and primary tumor tissues." (PMID 37781040, 2023). "Taken together, these findings suggest that NUSAP1 may play an important role in the process of tumorigenesis and tumor development." (PMID 37781040, 2023). "In the analysis of the immunomodulatory function, we found an association between NUSAP1 expression and immune score of various tumors, indicating that NUSAP1 may have a role in modulating the tumor microenvironment." (PMID 37781040, 2023). "This suggests that targeting NUSAP1-mediated microtubule stability could be a novel approach for tumor treatment." (PMID 37781040, 2023). "For instance, the elevated expression of fatty acid-binding protein 5 (FABP5), nucleolar and spindle associated protein 1 (NUSAP1), and the oncoprotein cancerous inhibitor of protein phosphatase 2 (CIP2A) in the tumor tissue of CC patients is significantly associated with lymph node metastasis." (PMID 37234990, 2023). "Furthermore, Gene Set Enrichment Analysis (GSEA) suggests that NUSAP1 promotes cell proliferation, tumor cell invasion, and regulation of anti-tumor response." (PMID 37781040, 2023). "Furthermore, we disclose the predictive value of NUSAP1 for tumor prognosis and response to immune checkpoint blockade therapy based on survival data from TCGA and GEO databases." (PMID 37781040, 2023).
tumor (continued). "Interestingly, single-cell sequencing data of tumor tissues showed that NUSAP1 is highly expressed not only in malignant cells but also various immune cells." (PMID 37781040, 2023). "Interestingly, these results suggested that phosphorylation of NUSAP1 at Ser309 and Thr312, located in the microtubule-associated domain, was significantly elevated in HNSC tumor tissue compared with normal tissue." (PMID 37781040, 2023). "Finally, NUSAP1 has been proposed as a carcinogenic element whose overexpression would help tumor progression in triple-negative BC cells, participating in the epithelial-mesenchymal transition and the Wnt/β-catenin pathways." (PMID 36478748, 2022). "This indicates that NUSAP1 plays a complex change in tumor immunity." (PMID 35710427, 2022). "At the same time, NUSAP1 may be involved in immune escape and affect the tumor microenvironment, so immune checkpoint inhibitor therapy may have a better effect." (PMID 35710427, 2022). "In this study, we found that high NUSAP1 expression was significantly correlated with tumor pathological stage, lymph node metastasis, and pathological grade; NUSAP1 expression was significantly higher in patients with T3-T4 TNM stage, higher pathological grades, and positive lymph nodes (p < 0.05)." (PMID 35487972, 2022). "NUSAP1 participated in the formation of the tumor microenvironment." (PMID 35710427, 2022). "NUSAP1 showed a strongest correlation with neutrophil tumor infiltration." (PMID 35739489, 2022). "NUSAP1 promoted tumor cell migration and invasion, while microRNA-569 over-expression could reverse this effect by directly binding with its 3’-UTR." (PMID 35483343, 2022). "It was proved that NUSAP1 reduction noticeably restricted tumor formation in vivo." (PMID 34782617, 2021). "This study also demonstrates the link between NUSAP1 and tumor cell migration and invasion." (PMID 34322597, 2021). "Firstly, we generated a dot plot according to expression level of NUSAP1 in 52 normal samples and 115 HCC samples by GraphPad Prism; the result showed that expression level of NUSAP1 in tumor samples was significantly higher than that in normal samples (p < 0.0001)." (PMID 34354737, 2021). "In general, NUSAP1 is differentially expressed in tumor and adjacent normal tissues." (PMID 32226503, 2020). "The results showed that NUSAP1 depletion significantly inhibited tumor formation in vivo." (PMID 32317623, 2020). "Collectively, our data indicated that NUSAP1 depletion retarded tumor cell growth in vivo." (PMID 33489890, 2020). "This study indicates that NUSAP1 acts as a tumor promoter in GBM." (PMID 32317623, 2020). "NUSAP1 is an important microtubule-associated protein; its role in PCa is suggested to be via induction of FAM101B that modulates cell shape and is involved in the TGF-β pathway promoting tumor invasion." (PMID 29545934, 2018). "Interestingly, we identified FAM101B, a TGFβ1 signaling effector, as a potential downstream effector of NUSAP1 in tumor progression." (PMID 28404898, 2017). "Our analyses suggest NUSAP1 overexpression may lead to tumor progression in patients, at least in part, via FAM101B." (PMID 28404898, 2017). "NUSAP1 expression is positively correlated with tumor progression and recurrence." (PMID 27863408, 2016). "Moreover, down-regulated NUSAP1 expression suppresses tumor proliferation and also enhances anti-tumor effect of PTX by activating apoptotic pathways." (PMID 26554377, 2015). "The present study shows that NUSAP1 is overexpressed in OSCC and that the altered NUSAP1 expression profile is closely associated with tumor size in primary OSCC samples, suggesting that NUSAP1 may be a crucial biomarker for OSCC." (PMID 26554377, 2015). "In other words, down-regulated NUSAP1 expression can enhance the anti-tumor activity of PTX with its synergistic effects, and might overcome chemoresistance to PTX in OSCCs." (PMID 26554377, 2015).
tumor (continued). "So we assume that the accelerated tumor cell proliferation may be controlled by decreasing NUSAP1 expression." (PMID 26554377, 2015). "Moreover, NUSAP1 can modulate downstream transcription factors to activate multiple signaling pathways, thereby inducing cancer cell stemness and contributing to early tumor recurrence." (PMID 40535133, 2025). "Consequently, NUSAP1 is involved in nearly every stage of tumor initiation and progression." (PMID 40535133, 2025). "Additionally, NUSAP1 influences the immune microenvironment, facilitating tumor immune escape." (PMID 40535133, 2025). "Many downregulated genes in tumour‐infiltrating peripheral CD8+ T cells are associated with classical IFN responses (IFI6, IFI27, MX1, STAT1, EPSTI1 PARP9, ISG15), cell proliferation (STMN1, CENPF, HELLS, NUSAP1, and DNPH1), and T cell costimulation (CD28, TMIGD2, TNFRSF4, CD27, and TNFRSF18)." (PMID 39350478, 2024). "Tumor cells satisfy their energy needs for rapid proliferation by upregulating glycolysis and lactate production, and the produced lactate serves as a signaling molecule, continuously driving the Warburg effect by inducing lactylation of key proteins such as NUSAP1." (PMID 39010066, 2024). "Additionally, given that NUSAP1 may play a role in regulating the tumor microenvironment, modulating NUSAP1 expression may represent a promising therapeutic strategy to be combined with ICIs." (PMID 39430250, 2024). "Therefore, targeting the lactate metabolism and signaling pathways of tumor cells may be an effective strategy for PC treatment, such as targeting NUSAP1 or inhibiting LDHA." (PMID 39010066, 2024). "Therefore, our systematical analysis indicates that NUSAP1 could serve a reliable predictive biomarker for prognosis and tumor immunotherapy response." (PMID 37781040, 2023). "However, the role of NUSAP1 in the tumor microenvironment is complex." (PMID 35710427, 2022). "In addition, NUSAP1 also played essential roles in tumor progression." (PMID 35431924, 2022). "NUSAP1 may have an effect on tumor cell growth by affecting the cell cycle and DNA damage repair." (PMID 35710427, 2022). "Hence, in order to further explore the mechanism of NUSAP1 influencing HCC progress, we used HCC patients’ information from GSE76427 dataset, ICGC database, and TCGA database to accomplish GSEA enrichment analysis and found that NUSAP1 promoted tumor progression by regulating cell cycle." (PMID 34354737, 2021). "Consequently, NUSAP1 depletion suppressed tumor progression in GBM." (PMID 32317623, 2020). "Furthermore, overexpression of NUSAP1 was observed in the advanced tumor samples." (PMID 26554377, 2015). "For instance, nucleolar and spindle associated protein 1 (NUSAP1), is a nucleolar-spindle-associated protein that plays a role in spindle microtubule organization that is positively correlated with hsa-miR-18a in normal but not in tumour." (PMID 22452920, 2012). "Mechanistically, it has been shown that NUSAP1 can stabilize NOTCH2 by inhibiting its ubiquitination, thereby activating NOTCH2 signaling and promoting tumor progression and chemoresistance." (PMID 41200204, 2025). "The interaction between NUSAP1 and MEF2D enhances the activity of the Wnt/B-catenin signaling pathway, promoting tumor progression." (PMID 40535133, 2025). "The growth rates and tumor weights of A549 and MCF-7 tumors in nude mice were significantly reduced after NUSAP1 knockdown." (PMID 37781040, 2023). "Four hub genes, including TTK, BUB1B, NUSAP1, and ZWINT, were revealed as tumor-promotive factors in OC, having the potential to be utilized as novel biomarkers and therapeutic targets for OC management." (PMID 37304238, 2023). "Brain MRI at 16 days and H&E staining of the tumors showed that tumor volume in the LINC01393-KD+NC group was significantly smaller than that in the NC group and the LINC01393-KD+NUSAP1-OE group." (PMID 36982952, 2023).
tumor (continued). "Kaplan–Meier and log-rank tests showed that the 5-year survival rates of patients with high NUSAP1 expression, FIGO III-IV, and residual tumor size > 1 cm were significantly decreased." (PMID 35739489, 2022). "On the contrary, NUSAP1 and YWHAE were over-expressed in primary tumor tissues compared to the peritoneal metastatic lesions, which was in accordance with our findings from bioinformatic analysis." (PMID 35515139, 2022). "NUSAP1 and PCLAF expression patterns were compared against tumor relapse for disease-free survival and death due to BC for OS." (PMID 36478748, 2022). "In the multivariate Cox′s proportional hazards model analysis, NUSAP1 expression level, FIGO stage, and residual tumor size were found to be independent prognostic factors." (PMID 35739489, 2022). "It was found that the expression of NUSAP1 and ZWINT was significant higher (p < 0.05) in tumours specimens compared with para-cancer tissues." (PMID 35431924, 2022). "Patients achieving pCR showed downregulation of NUSAP1 and PCLAF in tumor tissues and increased DFS and OS, while overexpression of these genes correlated with poor therapeutic response and OS." (PMID 36478748, 2022). "The dot plot of NUSAP1 expression level in 304 normal samples and 732 HCC samples showed expression level of NUSAP1 in tumor samples was significantly higher than that in normal samples (p < 0.0001)." (PMID 34354737, 2021). "Our previous research screened four genes from ENZ-resistant C4-2B cells, which were CCNA2, CKAP2L, NCAPG, and NUSAP1, and confirmed that the protein levels of these four genes also remained higher in ENZ-resistant xenograft tumor tissues." (PMID 34746227, 2021). "The dot plot of NUSAP1 expression level in 50 normal samples and 374 HCC samples showed expression level of NUSAP1 in tumor samples was significantly higher than that in normal samples (p < 0.0001), which was same as the result we got by GSE76427 dataset." (PMID 34354737, 2021). "Several proteins already known to promote tumor metastasis (NOTCH2, NCS1, NUSAP1, CD151), were increased more than 10-fold under hypoxic conditions, further demonstrating the potent effects of oxygen restriction on cancer cell biology." (PMID 31666928, 2019). "NUSAP1 expression was significantly increased in DCIS and IDC in our study and is therefore a promising new tumour marker." (PMID 21314937, 2011). "The research results suggest that NUSAP1 may activate the TGF-B signaling pathway by directly up-regulating TGFBR1, thereby mediating the EMT process and promoting tumor cell proliferation, migration, and invasion." (PMID 40535133, 2025). "Moreover, NUSAP1 is likely to synergistically promote EMT via both pathways, thereby enhancing tumor cell proliferation, migration, and invasion." (PMID 40535133, 2025). "In order to further confirm the biological functions of NUSAP1, we established a xenograft tumor model by inoculating PANC-1 cells that transfected with empty vector or the NUSAP1 shRNA into nude mice and monitored tumor size for 28 days." (PMID 38229038, 2024). "However, upregulated NUSAP1 expression partially reversed the effect of LINC01303-KD, leading to the increased tumor volume and shorten survival." (PMID 36982952, 2023). "In addition, increased NUSAP1 and DHX9 mRNA levels were significantly correlated with higher tumor Gleason scores, while increased ILF2 were less correlated with tumor Gleason scores." (PMID 37047232, 2023). "After validation, our studies showed that downregulation of NUSAP1 and PCLAF (Previous Symbol HGNC: KIAA0101) and overexpression of MME and DST in tumor biopsies of patients significantly correlated with pCR after NCT disease-free survival (DFS) and overall survival (OS)." (PMID 36478748, 2022).
tumor (continued). "We assessed the relevance between NUSAP1 and the tumor microenvironment using ESTIMATE, correlations between NUSAP1 and immune cells with TIMER, the relationship between NUSAP1 and immunotherapy by TCIA, and small-molecule drugs targeting NUSAP1 that can be discovered using the CMap database." (PMID 35710427, 2022). "To further investigate whether NUSAP1 impacts on the growth of CLL cells in vivo, we observed the effects of NUSAP1 on tumor formation in SCID Beige implantation models." (PMID 34782617, 2021). "Many of the key regulators in the canonical oncogenic (tan) module were involved in the processes leading to tumor cell proliferation and survival (TPX2, NCAPH, KIF11, NUSAP1, KIF23, MCM10) but most of them have not been associated with pediatric tumors." (PMID 31988326, 2020). "Despite NUSAP1, GPR65 proved to promote tumor growth in cancer." (PMID 30356407, 2018). "To confirm whether NUSAP1 promotes tumor aggressiveness by activating the HH pathway, we induced knockdown of the expression of GLI1 by small interfering RNA in NUSAP1-transduced SW1008 cells." (PMID 28899410, 2017). "Current studies primarily focus on how NUSAP1 influences tumor progression by modulating the post-translational modifications of other proteins; however, no research has directly established a link between NUSAP1’s own post-translational modifications and tumor progression." (PMID 40535133, 2025). "In addition, studies have confirmed that the positively correlated co-expression genes NUSAP1, ASF1B, TPX2, and SKA1 are invariably involved in immune cell infiltration in numerous cancers, and thus contribute to the regulation of the tumor immune microenvironment." (PMID 38173030, 2024). "Three of those genes, PCNA, ATP5C1, and NUSAP1, were confirmed to be co-expressed with TOX in tumour samples, but not in normal skin and atopic dermatitis, and as a result, they have a potential to be a diagnostic marker in CTCL." (PMID 32751918, 2020).